TINCR (TINCR ubiquitin domain containing)
Description:
Promotes epithelial differentiation by enhancing the sumoylation and activation of CDC42. Promotes keratinocyte proliferation. This contributes to the maintenance of skin homeostasis by enhancing wound healing after skin injury (By similarity). Acts as a tumor suppressor in epithelial tumors.
Synonyms: LINC00036; NCRNA00036; PLAC2; FLJ90734; onco-lncRNA-16; TUBL
Gene: Protein-coding gene on chromosome 19 (5,558,167 to 5,578,349, reverse strand). Ensembl gene ENSG00000223573.
Subcellular location: Nucleus; Cell junction; Cytoplasm
Gene Ontology:
Biological process: positive regulation of keratinocyte proliferation; positive regulation of wound healing
Cellular component: anchoring junction; nucleus; cytoplasm
Homologues: Orthologues: chimpanzee TINCR (100% identical), pig TINCR (98% identical), mouse Tincr (90% identical), rat Tincr (89% identical).
Diseases named in the same sentence as TINCR in open-access papers:
TINCR is named in the same sentence as 59 diseases in open-access papers, as found by Europe PMC text mining. Sharing a sentence is not in itself a finding about the gene and the disease. The quoted sentences say what the papers report.
breast cancer (30 papers, 2015 to 2025). A primary or metastatic malignant neoplasm involving the breast. "Recently, aberrant expression of TINCR was shown to be associated with the progression of several types of cancer such as breast cancer and hepatocellular carcinoma." (PMID 36675313, 2023). "The association of TINCR overexpression with patient survival was analyzed in 125 patients with breast cancer in the HMUCC cohort." (PMID 33446634, 2021). "The CREB-binding protein-mediated H3K27 acetylation at the promoter region of TINCR has been suggested as the underlying mechanism for over-expression of TINCR in breast cancer." (PMID 32695943, 2020). "A great deal of evidence shows that aberrant expression of TINCR is associated with a variety of human cancers, including breast cancer." (PMID 32929060, 2020). "Particularly, TINCR was associated with unfavorable prognosis in breast cancer, which is consistent with the implication of TINCR in promoting breast cancer tumorigenesis." (PMID 32231885, 2020). "Four CpG sites located nearest the genes CTNNA2, GRB10, RPH3AL, and TINCR showed individual associations with breast cancer risk in a multivariable model (P < 0.05) and were also associated with breast cancer risk in matched case-control pairs in EPIC-Italy." (PMID 31039828, 2019). "As an oncogenic lncRNA, TINCR has been identified as a subtype-specific lncRNA associated with the triple-negative and luminal B subtypes of breast cancer." (PMID 32038996, 2019). "Next, we attempted to elucidate the potential regulatory mechanism underlying aberrant overexpression of TINCR in breast cancer." (PMID 29614984, 2018). "TINCR can be used as a diagnostic marker and therapeutic target for breast cancer." (PMID 33649294, 2021). "TINCR can be used as a diagnostic marker and treatment target of breast cancer, as well as provide experimental basis for clinical diagnosis and treatment of breast cancer." (PMID 33649294, 2021). "The authors further noted that serum TINCR levels were associated with unfavorable prognosis, suggesting that TINCR could serve as a novel biomarker for breast cancer therapy." (PMID 34527584, 2021). "The long noncoding RNA (lncRNA) TINCR has recently been found to be associated with the progression of human malignancies, but the molecular mechanism of TINCR action remains elusive, particularly in breast cancer." (PMID 33446634, 2021). "For example, the distant metastasis-free survival, overall survival, and progression-free survival of breast cancer patients are strongly associated with high expression of BCAR4, LUCAT1, and TINCR." (PMID 38233788, 2024). "This is the first study to describe the regulatory role of TINCR in breast cancer tumor immunity, broadening the current paradigm of the functional diversity of TINCR in tumor biology." (PMID 36725842, 2023). "These functions of miR-7 in breast cancer (BC) can be diminished by the expression of lncRNA TINCR, which is enhanced by the Sp1 transcription factor." (PMID 37384249, 2023). "We used qRT-PCR to examine the effect of STAT1 knockdown on TINCR expression in breast cancer cells." (PMID 36725842, 2023). "Based on this mechanism, we emphasize the potential of TINCR as a target for breast cancer immunotherapy, specifically by combining TINCR knockdown with a PD-L1 inhibitor." (PMID 36725842, 2023). "We also revealed that, as part of the upstream regulatory mechanism, the INF-γ–STAT1 signaling axis promoted TINCR transcription in breast cancer." (PMID 36725842, 2023). "We confirmed that TINCR upregulated PD-L1 expression in vivo and in vitro, and promoted the progression of breast cancer." (PMID 36725842, 2023). "The combination of TINCR knockdown and PD-L1 inhibition showed a synergistic inhibitory effect on breast cancer progression." (PMID 36725842, 2023). "Next, we revealed that TINCR knockdown can significantly improve the therapeutic effect of PD-L1 inhibitors in breast cancer in vivo." (PMID 36725842, 2023).
breast cancer (continued). "In this study, we found that TINCR was expressed in both the cytoplasm and nucleus of breast cancer cells." (PMID 36725842, 2023). "And breast cancer-related TINCR ubiquitin domain containing (TINCR) impaired the efficacy of immunotherapy via posttranslational modification of programmed cell death 1 ligand 1 (PDL1)." (PMID 37036576, 2023). "Our previous studies and other reports demonstrate that noncoding RNAs also regulate trastuzumab resistance to breast cancer, e.g., miR-200c, miR-221, miR-375, lncRNA TINCR, AGAP2-AS1, and UCA11,3,10,11,29,30." (PMID 36309503, 2022). "Several studies have reported that TINCR plays a cancer suppressive role in lung cancer, breast cancer, and prostate cancer by inhibiting biological characteristics, such as proliferation, migration, and invasion of cancer cells." (PMID 35101062, 2022). "Previous studies and our nuclear cytoplasmic separation experiments as well as RNA IP have confirmed that TINCR mainly exists in the cytoplasm in breast cancer cells, and is involved in posttranscriptional gene regulation by binding with STAU121." (PMID 33649294, 2021). "TINCR expression is upregulated in gastric, gladder and breast cancer but downregulated in glioma and prostate cancer." (PMID 34527584, 2021). "Our study found high expression of lncRNA TINCR in breast cancer and its expression level is related to age, tumor size, and TNM stage." (PMID 33649294, 2021). "This study found that TINCR was significantly upregulated in breast cancer tissues, and the upregulated TINCR was closely related to the age of onset, tumor volume, and TNM stage." (PMID 33649294, 2021). "Here, we focused on TINCR, which was found to be expressed at higher levels in human breast-cancer than in normal tissues." (PMID 33446634, 2021). "Further experiments showed that TINCR promoted the proliferation and metastasis of breast cancer cells by regulating its target gene OAS1." (PMID 33649294, 2021). "In purpose to determine the target genes regulated by TINCR, we used RNA transcriptome sequencing (RNA-seq) technology to detect the gene expression profiles of breast cancer cells in which TINCR expression was suppressed." (PMID 33649294, 2021). "In conclusion, TINCR plays a role of oncogene in breast cancer and can be used as a potential biomarker for diagnosis and treatment." (PMID 33649294, 2021). "To explore the function of TINCR in breast cancer cells, we first performed qRT-PCR analysis to detect its expression level in diverse human breast cancer cell lines." (PMID 33649294, 2021). "High level of TINCR can promote proliferation and metastasis of breast cancer cells, while downregulation of TINCR induces G1-G0 arrest and apoptosis." (PMID 33649294, 2021). "Flow cytometry revealed that the proportion of apoptotic cells treated with si-TINCR 1# and 2# was remarkably increased in breast cancer cells." (PMID 33649294, 2021). "Here, we uncovered the diverse manners in which the lncRNA TINCR functions in breast cancer biology." (PMID 33446634, 2021). "The results showed that TINCR was significantly overexpressed in breast cancer tissues compared to that in adjacent normal tissues." (PMID 33649294, 2021). "Subsequently, we performed qRT-PCR analysis in 60 pairs of breast cancer tissues and found that the expression of TINCR was increased in 38 breast cancer tumor tissues compared to the noncancerous lesions." (PMID 33649294, 2021). "Further analysis revealed that TINCR expression was inversely correlated with OAS1 level in breast cancer (Pearson correlation coefficient r = −0.697, r2 = 0.485, P < 0.001)." (PMID 33649294, 2021). "In order to explore the oncogene role of TINCR in breast cancer, we carried out the function deletion/expression experiment." (PMID 33649294, 2021). "TINCR is upregulated in human breast cancer tissues, and TINCR knockdown suppresses tumorigenesis in vitro and in vivo." (PMID 33446634, 2021).
breast cancer (continued). "As lncRNAs participate in many biological processes, we investigated the influence of TINCR on breast cancer in vitro." (PMID 33649294, 2021). "First, the subcellular localization of TINCR was examined, which revealed TINCR localization in both the cytoplasm and the nucleus in breast-cancer cells." (PMID 33446634, 2021). "Several studies have shown that TINCR is significantly upregulated in breast cancer and plays as an oncogene, and its upregulated expression is believed to be mainly caused by gene amplification." (PMID 33649294, 2021). "In our study, we find out that TINCR expression was inversely correlated with OAS1 level in breast cancer tissues." (PMID 33649294, 2021). "They found that TINCR was overexpressed in breast cancer tissues and cell lines, and that high levels of TINCR were associated with a relatively poor prognosis." (PMID 33649294, 2021). "To further explore the role of TINCR in breast cancer, we evaluated the relationship between TINCR expression and clinicopathological characteristics of breast cancer patients." (PMID 33649294, 2021). "To further explore the mechanism of TINCR in breast cancer, we first determined the distribution of TINCR in breast cancer cells." (PMID 33649294, 2021). "Another study in breast cancer demonstrated the role of TINCR in stimulation of tumorigenesis through modulating expression of miR-125b and its target gene ERBB2." (PMID 32695943, 2020). "During breast cancer cell metastasis, lncRNA TINCR upregulation is attributed to the transcriptional activation by the CREB-binding protein-mediated H3K27 acetylation enrichment." (PMID 32929060, 2020). "Two independent in vivo studies in breast cancer reached the similar results confirming the oncogenic role of TINCR in this kind of cancer." (PMID 32695943, 2020). "In line with previous investigations into other tumors, our results from both clinical samples and cell lines demonstrated the consistent up-regulation of TINCR in breast cancer." (PMID 29614984, 2018). "Most importantly, our data suggested that either specific inhibition of TINCR or complement with miR-7 likely held great promise for breast cancer therapeutics." (PMID 29614984, 2018). "Consistent with previous results, TINCR-knockdown significantly suppressed breast cancer cell proliferation, while simultaneous inhibition of miR-7 in this setting almost abolished this effect." (PMID 29614984, 2018). "Here we set out to determine the expression status of TINCR and sought to elucidate its mechanistic linkage to breast cancer." (PMID 29614984, 2018). "Our results clearly demonstrated the critical role of TINCR in tumorigenesis and metastasis-related malignant behavior in breast cancer, and predominant role of miR-7 in mediating this effect." (PMID 29614984, 2018). "The inhibitory effects on invasive behavior of breast cancer cells imposed by TINCR-knockdown was almost abrogated as well." (PMID 29614984, 2018). "Here we for the first time demonstrated over-expression of TINCR in both breast cancer tissues and cell lines." (PMID 29614984, 2018). "In summary, our data demonstrated that inhibition of TINCR blocked malignant progression in breast cancer." (PMID 29614984, 2018). "Our previous data demonstrated that TINCR knockdown significantly suppressed cell proliferation, anchorage-independent growth and stimulated spontaneous apoptosis in breast cancer cells." (PMID 29614984, 2018). "Here we set out to analyze expression of TINCR in breast cancer and elucidate its mechanistic involvement in tumor incidence and progression." (PMID 29614984, 2018). "Our data unambiguously demonstrated that miR-7 predominately involved in oncogenic activity of TINCR in breast cancer." (PMID 29614984, 2018). "Consistent with transwell assay, the wound closure was decelerated in TINCR-deficient cells in comparison with control, which indicated the crucial role of TINCR in maintenance of cell migration in breast cancer." (PMID 29614984, 2018).
breast cancer (continued). "Next, we sought to determine the extent that this regulatory axis was involved in the oncogenic activity of TINCR in breast cancer." (PMID 29614984, 2018). "Our data suggested a crucial role of TINCR-miR-7-KLF4 axis in human breast cancer and up-regulation of ceRNA TINCR by SP1 contributes to tumorigenesis in breast cancer." (PMID 29614984, 2018). "In this study, we found that TINCR could promote the proliferation and metastasis of breast cancer cells and was positively correlated with PD-L1 expression." (PMID 36725842, 2023). "Therefore, TINCR knockdown enhances PD-L1 inhibitor sensitivity in breast cancer, producing a synergistic anticancer effect." (PMID 36725842, 2023). "Besides this, TINCR knockdown enhanced sensitivity to PD-L1 inhibitor sensitivity in an in vivo model of breast cancer." (PMID 37835376, 2023). "In breast cancer cells, TINCR was localized in both the cytoplasm and nucleus." (PMID 36725842, 2023). "As a carcinogenic factor, TINCR can promote the progression of breast cancer in vivo and in vitro." (PMID 37901333, 2023). "It has been reported that TINCR promotes the resistance of breast cancer to cisplatin, but the effect of TINCR on CM cisplatin resistance remains unknown." (PMID 35067169, 2022). "Therefore, we started to study the expression level of TINCR in breast cancer and tried to clarify the mechanism of TINCR involved in the occurrence and development of breast cancer." (PMID 33649294, 2021). "We found that TINCR expression was upregulated in breast cancer tissues and cell lines." (PMID 33649294, 2021). "Our study focused on the function and mechanism of TINCR in breast cancer." (PMID 33649294, 2021). "The oncogenic role of TINCR was examined in vitro and in vivo in breast cancer." (PMID 33446634, 2021). "However, the research on the expression pattern and mechanism of TINCR in breast cancer is very limited." (PMID 33649294, 2021). "In vitro and in vivo experiments showed that overexpression of TINCR can promote the proliferation of breast cancer cells, and this effect may be achieved by regulating cell cycle and apoptosis." (PMID 33649294, 2021). "However, there are few researches on the upstream regulation mechanism of TINCR in breast cancer, it will be one of the focuses of future research." (PMID 33649294, 2021). "We divided 60 breast cancer patients into TINCR high expression group (n = 38) and TINCR low expression group (n = 22), according to whether TINCR expression was upregulated or downregulated compared with the corresponding adjacent noncancerous tissue samples." (PMID 33649294, 2021). "Our findings enrich the molecular mechanism of TINCR in regulating breast cancer progression." (PMID 33649294, 2021). "SP1 has a similar role in induction of TINCR expression in breast cancer cell lines." (PMID 32695943, 2020). "Through this molecular axis, TINCR inhibits apoptosis in breast cancer cells." (PMID 32695943, 2020). "Finally, TINCR has been shown to be over-expressed in trastuzumab-resistant breast cancer cells compared with sensitive cells." (PMID 32695943, 2020). "Taken together, our data demonstrated SP1 stimulated TINCR overexpression in breast cancer." (PMID 29614984, 2018). "Next, we sought to understand the potential oncogenic role of TINCR in breast cancer." (PMID 29614984, 2018). "Our data uncovered a crucial role of TINCR-miR-7-KLF4 axis in human breast cancer." (PMID 29614984, 2018). "We further determined the expression pattern of TINCR in panel of breast cancer cell lines." (PMID 29614984, 2018). "TINCR was markedly over-expressed in breast cancer with 3~ 16-fold increase." (PMID 29614984, 2018). "The expression level of TINCR was examined in breast cancer lines." (PMID 28738804, 2017). "Moreover, TINCR, LINC00511, and PPP1R26-AS1 were identified as subtype-specific lncRNAs associated with HER-2, triple-negative and luminal B subtypes of breast cancer, respectively." (PMID 28738804, 2017).